ULBP1 (UL16 binding protein 1)
Diseases named in the same sentence as ULBP1 in open-access papers (continued):
Sharing a sentence is not in itself a finding about the gene and the disease.
infection (continued). "In contrast, four (ULBP1, EGR3, RAET1K, EGR2) genes were downregulated in uninfected cells (GFP- pHrodo-) relative to the other three infection outcomes." (PMID 40630957, 2025). "We recently studied HHV-6B, a closely related β-herpesvirus, which targets ULBP1, ULBP3 and MICB during infection." (PMID 34721381, 2021). "In this study, we identify two HHV-6A encoded immunoevasins, U20 and U21, which suppress the expression of the NKG2D ligands ULBP1 and ULBP3, respectively, during infection." (PMID 34721381, 2021). "Twenty-four hours following infection, we stained the mock-infected and the infected cells for the expression of NKG2D ligands: MICA, MICB, ULBP1, ULBP2, ULBP3, and ULBP4." (PMID 32698530, 2020). "While ULBP-1, ULBP-2/5/6, and ULBP-3 are rarely expressed on healthy primary CD4+ T cells, it is well established that infection with several laboratory strains of HIV can induce their surface expression." (PMID 29023371, 2017). "Additionally, five genes (CCL26, MIR8485, ULBP1, CCL13, CISH) and one unannotated gene (ENSG00000289505) were downregulated in the transwell relative to the other infection groups." (PMID 40630957, 2025). "In this experiment, the infection efficiency was 47.6% These findings confirm that ULBP1 is not degraded during HHV-6B infection and that any surface downregulation of ULBP1 must utilize an alternative mechanism." (PMID 38953028, 2024). "First, we performed an anti-ULBP1 western blot, which showed that ULBP1 protein levels do not decrease during infection, and in fact increase by 20% relative to a tubulin control when compared to the mock infected cells." (PMID 38953028, 2024). "Interestingly, we observed a strong decrease of all MICB, ULBP1 and ULBP3 total protein following infection with HHV-6A (quantified in the bar diagram) indicating that there is no intracellular retention, but actual reduction in overall protein levels." (PMID 34721381, 2021). "SV/mKate infection also did not lead to reduced ULBP1 expression, indicating that the SV40 capsid proteins are not responsible for ULBP1 downregulation." (PMID 26992229, 2016). "Nevertheless, we have gathered data that indicate that SV40 infection leads to an MOI-dependent reduction of ULBP1 levels, that ULBP1 is not arrested inside the cells and that the infection results in a reduction of ULBP1 mRNA levels." (PMID 26992229, 2016). "Although exogenous expression of Rh159 reduced ULBP1 surface levels, infection with RhCMV in the absence of Rh159 did not lead to increased ULBP1 surface levels compared to RhCMV." (PMID 27580123, 2016). "To ascertain if differences in receptor-ligand interactions could be responsible for the impaired capacity of the NK cells to kill the TCD32dim subset, we studied the expression of MICA/B, ULBP-1, CD155, and HLA-E on the surface of HIV-infected CD4+ T cells after ex vivo infection." (PMID 35616530, 2022). "No significant change in ULBP1 or PVR surface expression was detected and a slight increase in ULBP3 levels during infection with both strains was noticed." (PMID 28819195, 2017). "Like MYXV, infection with vMyx-M153KO did not affect expression of other NK ligands including HLA–E, MICA/B, ULBP1–3, and PVR (not shown)." (PMID 23762498, 2013). "It is still unknown how the infected cells sense the infection and react by upregulating the mRNAs of several NKG2D ligands and it is also unknown why the expression of ULBP1 is not changed." (PMID 32698530, 2020).
ULBP1 also shares sentences with these, for which no sentence is quoted: B-cell chronic lymphocytic leukemia (2 papers); acute leukemia (1); acute T-cell leukemia (1); adenocarcinoma (1); anaplastic large cell lymphoma (1); bladder tumor (1); brain tumors (1); cervical intraepithelial neoplasia (1); chronic hepatitis B (1); colorectal tumors (1); COVID-19 (1); gastric tumor (1); hepatitis C virus infection (1); immune diseases (1); liver fibrosis (1); lung squamous cell carcinoma (1); myelodysplastic syndrome (1); neuroblastoma (1); oral cancer (1); ovarian tumors (1); rectal adenocarcinoma (1); rhabdomyosarcoma (1); Sjogren syndrome (1); skin cutaneous melanoma (1); systemic scleroderma (1); thyroid carcinoma (1); tonsil (1); tonsil cancer (1); uterine corpus endometrial carcinoma (1); vasculitis (1).